RNU1-95P (RNA, U1 small nuclear 95, pseudogene)
Gene: Small nuclear RNA gene on chromosome Y (18,116,848 to 18,117,007, forward strand). Ensembl gene ENSG00000252166.
Homologues: Orthologues: chimpanzee U1 (98% identical), macaque U1 (83% identical). Paralogues in human: RNU1-128P (100% identical), RNU1-40P (89% identical), RNU1-97P (89% identical), RNU1-41P (88% identical), RNU1-48P (88% identical), RNU1-1 (83% identical), RNU1-2 (83% identical), RNU1-27P (83% identical), RNU1-28P (83% identical), RNU1-3 (83% identical), RNU1-4 (83% identical), RNVU1-18 (83% identical), and 132 more.